RN7SKP197 (RN7SK pseudogene 197)
Gene: Miscellaneous RNA gene on chromosome 12 (119,631,090 to 119,631,386, reverse strand). Ensembl gene ENSG00000252886.
Homologues: Orthologues: chimpanzee 7SK (98% identical), guinea pig 7SK (51% identical), mouse Gm54738 (37% identical). Paralogues in human: RN7SKP217 (57% identical), RN7SKP47 (57% identical), RN7SKP166 (57% identical), RN7SKP184 (56% identical), RN7SKP200 (56% identical), RN7SKP162 (56% identical), RN7SKP187 (55% identical), RN7SKP65 (55% identical), RN7SKP79 (55% identical), 7SK (55% identical), RN7SKP1 (55% identical), RN7SKP103 (55% identical), and 284 more.